ENSG00000285664 (novel transcript, antisense to FERMT2)
Synonyms: LOC105370500
Gene: Long non-coding RNA gene on chromosome 14 (52,791,756 to 52,945,210, forward strand). Ensembl gene ENSG00000285664.
Gene Ontology:
Biological process: SRP-dependent cotranslational protein targeting to membrane, signal sequence recognition
Cellular component: signal recognition particle, endoplasmic reticulum targeting